XPNPEP3 (X-prolyl aminopeptidase 3)
Description:
Catalyzes the removal of a penultimate prolyl residue from the N-termini of peptides, such as Leu-Pro-Ala. Also shows low activity towards peptides with Ala or Ser at the P1 position. [Isoform 1]: Promotes TNFRSF1B-mediated phosphorylation of MAPK8/JNK1 and MAPK9/JNK2, suggesting a function as an adapter protein for TNFRSF1B; the effect is independent of XPNPEP3 peptidase activity. May inhibit apoptotic cell death induced via TNF-TNFRSF1B signaling.
Synonyms: APP3; NPHPL1; ICP55
Tractability: Small molecule: a drug acting on it is in phase 2 or 3 trials; a structure with a bound ligand is known. PROTAC: ubiquitination databases record sites on it; its protein half-life has been measured.
Gene: Protein-coding gene on chromosome 22 (40,857,077 to 40,932,815, forward strand). Ensembl gene ENSG00000196236.
Subcellular location: Mitochondrion (Isoform 1); Cytoplasm; Cytoplasm (Isoform 2)
Subcellular location (Human Protein Atlas): Mitochondria; Cytosol
Gene Ontology:
Molecular function: aminopeptidase activity; manganese ion binding; metalloaminopeptidase activity; protein binding; protein homodimerization activity; metalloexopeptidase activity
Biological process: glomerular filtration; protein processing; proteolysis
Cellular component: cytoplasm; cytosol; mitochondrion
Genetic constraint (gnomAD): Loss-of-function variants: 39 observed, 61.31 expected, observed/expected ratio (o/e) 0.64, 90% interval 0.49 to 0.83. The upper end of that interval is the gene's LOEUF score, 0.83, which puts it in group 3 of 6, group 1 being the genes least tolerant of losing a copy. Missense variants: 598 observed, 675.19 expected, observed/expected ratio (o/e) 0.89, 90% interval 0.83 to 0.95. Synonymous variants: 212 observed, 236.51 expected, observed/expected ratio (o/e) 0.9, 90% interval 0.8 to 1.
Gene-disease validity (ClinGen):
ClinGen rates the evidence that XPNPEP3 causes each of these diseases.
nephronophthisis-like nephropathy 1 (autosomal recessive): Definitive.
Homologues: Orthologues: chimpanzee XPNPEP3 (99% identical), macaque XPNPEP3 (97% identical), dog XPNPEP3 (93% identical), rabbit XPNPEP3 (91% identical), mouse Xpnpep3 (91% identical), pig XPNPEP3 (89% identical), guinea pig XPNPEP3 (89% identical), rat Xpnpep3 (87% identical), tropical clawed frog xpnpep3 (68% identical), zebrafish xpnpep3 (57% identical), Caenorhabditis elegans icpp-55 (32% identical). Paralogues in human: PEPD (26% identical), XPNPEP2 (20% identical), XPNPEP1 (19% identical), METAP1D (11% identical), METAP1 (10% identical), METAP2 (10% identical), PA2G4 (8% identical).
Diseases named in the same sentence as XPNPEP3 in open-access papers:
XPNPEP3 is named in the same sentence as 22 diseases in open-access papers, as found by Europe PMC text mining. Sharing a sentence is not in itself a finding about the gene and the disease. The quoted sentences say what the papers report.
nephronophthisis (8 papers, 2013 to 2023). Progressive tubulointerstitial injury, inherited in an autosomal recessive pattern, caused by mutations in genes involved in ciliary function, which may result in an end stage renal failure. ",12Mutations of XPNPEP3 cause nephronophthisis-like nephropathy-1 (NPHPL1, OMIM: #613159), which is exceedingly rare." (PMID 37599822, 2023). "The N protein post-transcriptionally promotes XPNPEP3 (X-prolyl aminopeptidase 3), mutations in XPNPEP3 have somehow been implicated in the development of “nephronophthisis-like ciliopathy,” a cystic kidney disease." (PMID 34659373, 2021). "One study identified a single heterozygous variant in the XPNPEP3 gene (p.R155W) associated with severe nephronophthisis associated ciliopathy (NPHP-AC)." (PMID 34356047, 2021). "Recessive mutations in XPNPEP3 (MIM 613159) have been reported to cause nephronophthisis-like nephropathy 1 (NPHPL1)." (PMID 27799064, 2016). "Patients with XPNPEP3 deficiency, encoding X-prolyl aminopeptidase 3, develop a nephronophthisis-like nephropathy but can also involve other organs." (PMID 25778941, 2015). "ICP55 is the yeast ortholog of XPNPEP3 a gene mutated in a rare hereditary kidney disease resembling nephronophthisis with renal histopathology including tubular atrophy, tubular basement disruption and interstitial fibrosis." (PMID 24116217, 2013). "Finally, a recent study identify a new homozygous variant in the XPNPEP3 gene (p.Q241Tfs*13) associated with a paediatric nephronophthisis." (PMID 34356047, 2021). "Recessive pathological variants in XPNPEP3 give rise to a nephronophthisis-like nephropathy." (PMID 33426505, 2020).
ciliopathies (5 papers, 2015 to 2025). "Despite its localisation, evidence suggests that XPNPEP3 can process centrosomal proteins associated with cystic kidney diseases, linking the pathomechanism of NPHPL1 to other ciliopathies." (PMID 40857737, 2025). "However, longer primary cilia with abnormal Hh signaling were evoked by the aberrant expression of XPNPEP3 in either patient urine sediment cells or kidney tubular epithelial cells of Xpnpep3-KO mice, emphasizing the major role of XPNPEP3 homeostasis in mitochondrial function and ciliopathy." (PMID 37599822, 2023).
Nephropathy (4 papers, 2013 to 2021). A nonspecific term referring to disease or damage of the kidneys. "In this report, we have utilized S. cerevisiae as a simple model organism to characterize the phenotype of the icp55 deletion (icp55Δ) strain and gain insight into the pathogenetic mechanisms that contribute to the progressive kidney disease observed in the setting of XPNPEP3 mutations." (PMID 24116217, 2013). "Mutations in the X-Pro aminopeptidase 3, (encoded by the XPNPEP3 gene) have been associated with severe kidney disorders." (PMID 34356047, 2021). "In addition, we do not believe that this mitochondrial respiratory defect is likely to be the central mechanism mediating progression of XPNPEP3-related kidney damage for several reasons." (PMID 24116217, 2013).
acute kidney injury (2 papers, 2023 to 2025). Sudden and sustained deterioration of the kidney function characterized by decreased glomerular filtration rate, increased serum creatinine or oliguria. "Curiously, XPNPEP3 has been linked to nephronophthisis-like nephropathy-1 (NPHPL1, MIM #613159), an autosomal recessive cystic kidney disease characterised by early-onset renal failure with additional neurologic involvement." (PMID 40857737, 2025). "Strikingly, with the application of cisplatin (CDDP) to simulate mouse models of acute kidney injury (AKI), XPNPEP3−/−CDDP-AKI mice had obvious tubular dilation in HE staining and fibrosis in Masson staining compared with WT-CDDP-AKI mice." (PMID 37599822, 2023).
cardiomyopathy (2 papers, 2022 to 2023). A disease of the heart muscle or myocardium proper. "Considering the impacts of XPNPEP3 on mitochondria and cilia, extrarenal manifestations, such as cardiomyopathy and seizures as demonstrated in one NPHPL1 kindred, that may be caused by mitochondrial dysfunction were supposed to be observed." (PMID 37599822, 2023). "Several of the disorders associated with cardiomyopathy involve genes important for preprotein processing, such as MIPEP, XPNPEP3, CLPB, and HTRA2." (PMID 35328774, 2022). "Genes important in these processes and that are associated with cardiomyopathy include DNAJC19, MAGMAS, TIMM50, MIPEP, XPNPEP3, HTRA2, CLPB and HSPD1." (PMID 35328774, 2022).
bipolar disorder (1 paper, 2021). A disorder of the brain that causes unusual shifts in mood, energy, activity levels and the ability to carry out day-to-day tasks. "Also, only CEWAS found FAHD2B, HDAC5, MBTD1, NME2, and XPNPEP3 for bipolar disorder." (PMID 34807913, 2021).
depression (1 paper, 2021). "Among the seven TWS genes, upregulation of XPNPEP3 may be associated with depression risk as it has a positive Z-score (Z > 0 suggests that the gene is predicted to be upregulated in cases compared with controls)." (PMID 34021117, 2021). "Seven out of 53 risk genes (B3GALTL, FADS1, TCTEX1D1, XPNPEP3, ZMAT2, ZNF501 and ZNF502) showed TWS associations with depression in two independent brain expression quantitative loci (eQTL) datasets, suggesting that these genes may represent promising candidates." (PMID 34021117, 2021).
tubulointerstitial kidney disease (1 paper, 2013). "Recessive mutations in XPNPEP3, encoding a mitochondrial x-prolyl aminopeptidase, have been identified in families with a rare hereditary tubulointerstitial kidney disease." (PMID 24116217, 2013).
cancer (1 paper, 2019). A tumor composed of atypical neoplastic, often pleomorphic cells that invade other tissues. "We applied a hard filter to the GSMs and finally selected six genes (CLDN3, DECR2, EVA1B, NME4, NTSR1 and XPNPEP3) associated with epigenetic regulation, differentiation and cancer (Pearson’s correlation test; p-value ≤ 0.001)." (PMID 31040866, 2019).
tumor (1 paper, 2022). "The analysis of the transposon integration sites identified several candidate genes, of which Man1a1, Pkp4, Rab10, Rasa1, Trps1, Vps26a, Xpnpep3 and Znf326 accelerated tumor growth, whereas the silencing of R3hcc1l reduced tumor growth." (PMID 36497409, 2022).
XPNPEP3 also shares sentences with these, for which no sentence is quoted: cystic kidney disease (2 papers); nephronophthisis-like nephropathy 1 (2); Alzheimer disease (1); autosomal dominant polycystic kidney disease (1); bone cysts (1); familial intrahepatic cholestasis (1); kidney injury (1); liver disease (1); metabolic dysfunction-associated steatotic liver disease (1); neurodevelopmental disorder (1); renal failure (1); type 2 diabetes mellitus (1).